IL10 (interleukin 10)
Diseases named in the same sentence as IL10 in open-access papers (continued):
Sharing a sentence is not in itself a finding about the gene and the disease.
ulcerative colitis (127 papers, 2006 to 2026). An inflammatory bowel disease involving the mucosal surface of the large intestine and rectum. "Utilizing IL10-deficient mice, a classic model for ulcerative colitis, we found a substantial reduction in the number of PYY-positive cells in colonic tissues compared to control mice." (PMID 40340969, 2025). "In contrast, its decrease is associated with increased ulcerative colitis disease activity, which has been attributed to its immunomodulatory effects and its ability to induce IL-10 production in humans and mice." (PMID 41019955, 2025). "Previously, Fusicatenibacter sacchivorans, the only known species within the Fusicatenibacter genus, was shown to be increased in inactive ulcerative colitis (UC) patients and decreased in active UC, related to its positive association with IL-10 production." (PMID 32384826, 2020). "IL-10 is an important anti-inflammatory cytokine and IL-10R polymorphisms are associated with very early-onset ulcerative colitis." (PMID 32050001, 2020). "Lower IL-10 production is a risk for not only BD but also ulcerative colitis and other inflammatory diseases." (PMID 29895319, 2018). "Pathologically, Erbin expression in the intestinal mucosa was significantly decreased in DSS induced acute colitis mice, IL-10 deficient mice and clinical biopsy specimens from patients with ulcerative colitis." (PMID 29552291, 2018). "It was shown that performing such a procedure in patients with ulcerative colitis caused the appearance of T helper cells in the blood, which reacted to the content of sterile stool filtrates in an antigen-specific manner and produced IL-10." (PMID 38339169, 2024). "Moreover, dbGAP reveals a series of significant GWAS hits in and around IL-10, showing SNPs associated with Behcet’s disease and ulcerative colitis, some overlapping with IL-10 eQTLs." (PMID 29847580, 2018). "Furthermore, IL-10, which historically has been linked with anti-inflammatory properties, was associated with prolonged colonic transit time in our study, supporting similar findings in a cohort of individuals with ulcerative colitis." (PMID 37189645, 2023). "This shift reduces pro-inflammatory cytokines (TNF-α, IL-1β, IL-6), elevates anti-inflammatory IL-10, and mitigates mucosal damage, positioning miR-223 as a potent therapeutic candidate for ulcerative colitis (UC)." (PMID 40799643, 2025). "HSP90 inhibitors have been shown to ameliorate inflammation in ulcerative colitis by enhancing the secretion of the anti-inflammatory cytokine IL-10, increasing the number of regulatory T cells (Tregs), and attenuating inflammatory activation." (PMID 40458801, 2025). "The DRB1*01:03 allele—which is thought to be a risk allele for ulcerative colitis (UC) based on prior GWAS39—was associated with both UC and the expression of several inflammatory proteins such GZMA, GZMH, and IL10." (PMID 39085222, 2024). "Parallel to this, we have previously shown that M1 macrophages treated with FS from patients with ulcerative colitis increased IL-10 and pro-inflammatory cytokine secretion." (PMID 38201264, 2023). "Fusicatenibacter has been demonstrated to stimulate the production of the anti-inflammatory cytokine interleukin-10 (IL-10) in gut wall monocytes extracted from ulcerative colitis (UC) models in patients and mice." (PMID 37894244, 2023). "On 6 July 2022, Applied Molecular Transport (AMT) announced the results of the 2-stage MARKET test IL-10 inhibitor in patients with moderate to severe ulcerative colitis." (PMID 37457023, 2023). "Interleukin-6 was increased and interleukin-10 was decreased in mice of ulcerative colitis model group compared with the control group (P < .05)." (PMID 35946886, 2022). "Anthocyanin-rich bilberry extract was found to lower the levels of proinflammatory cytokines IFN-γ and TNF while increasing the levels of Th17 cell-specific cytokine IL-22 and immunoregulatory cytokine IL-10 in ulcerative colitis patients." (PMID 35204188, 2022).
ulcerative colitis (continued). "By contrast, OLE administration elicited an increase in tissue IL-10 mRNA in a model of acetic acid-induced ulcerative colitis and in tissue IL-10 protein in a model of DSS-induced chronic colitis together with a reduction in p38 MAPK phosphorylation." (PMID 36613822, 2022). "Recently, a study has shown induction of IL‐10 producing Tregs and wound healing macrophages in mouse models of ulcerative colitis in a TLR9‐dependent manner." (PMID 37406035, 2022). "In contrast, probiotic supplementation in ulcerative colitis generally decreases proinflammatory cytokines and raises IL-10 levels." (PMID 36005503, 2022). "This genus’ only known species, Fusicatenibacter saccharivorans, was reported to be positively associated with production of the anti-inflammatory cytokine IL-10 in ulcerative colitis patients." (PMID 35628138, 2022). "Aspirin markedly reduced interleukin-6 and enhanced interleukin-10 compared to the ulcerative colitis model group (P < .05) induced Azoxymethane/dextran sulfate sodium inflammation (3 weeks) and atypical hyperplasia (8 weeks)." (PMID 35946886, 2022). "Ulcerative colitis: Two widely used mouse models of ulcerative colitis are IL10 KO mice and dextran sodium sulfate (DSS)-induced colitis." (PMID 35625724, 2022). "It suggested that the free polyphenol extract of cherry likely acted as the inhibitor of IL-6 and TNF-α but the promotor of IL-10, and thus contributed to relieve ulcerative colitis induced by DSS in a cytokine-specific manner." (PMID 35010176, 2021). "Takeshita’s study revealed that the prevalence of F.saccharivorans was strikingly lower in active ulcerative colitis than quiescent ones, and suggested that human-derived F.saccharivorans can suppress intestinal inflammation, probably through IL-10 induction." (PMID 33747975, 2021). "While production of IFN-β and IL-10 was significantly decreased in the colonic mucosa of ulcerative colitis rats, their production was significantly upregulated upon herb-partitioned moxibustion." (PMID 33101289, 2020). "It produces a protein that inhibits the NF-κB pathway, stimulates production of anti-inflammatory cytokine IL-10, and inhibits ulcerative colitis in BALB/c mice." (PMID 33330572, 2020). "A high IL-10 serum level is maintained during the early phase of remission in some human ulcerative colitis patients, whereas C-reactive protein and IL-6 serum levels return to normal during remission after an increase during the acute phase." (PMID 31244763, 2019). "Our results showed that, compared with the healthy controls, IL-10 mRNA expression was significantly increased in ulcerative colitis patients (P < 0.05)." (PMID 29765931, 2018). "Our results demonstrated that serum IL-10 levels were significantly higher in ulcerative colitis patients than in controls (P < 0.05)." (PMID 29765931, 2018). "Based on the findings about the association between Breg and Th17 cells with pathogenesis of ulcerative colitis, the mRNA expression levels of IL-10 and RORγT were determined with qRT-PCR." (PMID 29765931, 2018). "Studies have shown that in ulcerative colitis, cytokines of the Th1 and Th17 patterns play an important role in the pathology of the disease, while Treg-like cytokines, such as IL-10, counterbalance the inflammatory process, reducing tissue damage." (PMID 30205459, 2018). "IL-10 has been shown to play a role in chronic gastrointestinal problems, and its modulation by probiotic bacteria has been observed in patients with ulcerative colitis and IBD." (PMID 30069221, 2018). "We recently developed a mouse model of IBD that phenotypically and histologically resembles human childhood-onset ulcerative colitis (UC), using mice that are genetically modified to be deficient in the cytokines TNF and IL-10 (“T/I” mice)." (PMID 27045690, 2016).
ulcerative colitis (continued). "In the second study (a phase IIa human clinical trial), ActoGenix (a company which develops genetically modified L. lactis for mucosal delivery of therapeutic molecules), assessed the effects of LAB IL-10 in subjects with moderately active ulcerative colitis." (PMID 25889561, 2015). "Many studies indicate that rise of IL-10 production in intestinal mucosa is correlated with protection in ulcerative colitis chemically induced in mice possibly as a result of clonal expansion of Treg subsets in intestinal mucosa." (PMID 25162711, 2014). "Following infection, germfree IL-10−/− NF-κBEGFP mice displayed mild symptoms at day 5 and ulcerative colitis at day 14 following C. jejuni strain 81–176 infection." (PMID 22808254, 2012). "Acute ulcerative colitis in diseased IL-10−/− mice was characterized by ulcerations of and bleeding into the colonic mucosa as well as diffuse mucosal and submucosal infiltrates, and, in additon, by loss of goblet cells and crypt drop-outs at day 7 p.i.." (PMID 22808254, 2012). "Topical IL-10 enema treatment of patients with ulcerative colitis unveiled that IL-10 is effective in down-regulating pro-inflammatory cytokine synthesis from IBD monocytes and lymphocytes both in vitro and in vivo." (PMID 17069659, 2006). "IL-10 knock-out mice develop chronic enterocolitis, and recent trials have investigated the possibility of using IL-10 as therapy in ulcerative colitis patients, another chronic inflammatory disease of the intestinal mucosa." (PMID 16579847, 2006). "As a result, this research utilized 11 serotonin derivatives to assess the effect of NO on LPS-stimulated RAW 264.7 cells and its role in regulating crucial cytokines linked to ulcerative colitis, specifically IL-6, TNF-α, IL-1β, and IL-10, through Griess and RT-qPCR assays." (PMID 40649400, 2025). "In a clinical trial of fecal transplantation in ulcerative colitis, it was discovered that Odoribacter is a type of metastatic bacteria that shapes mucosal immunity by increasing IL-10 expression and the production of SCFAs, resulting in an increase in regulatory T cells." (PMID 36839309, 2023). "For example, Wang and colleagues found that CD patients had significantly higher levels of IL-10 compared to controls and Kucharzik and coworkers reported increased serum IL-10 concentration in patients with active CD or ulcerative colitis (UC) compared to controls." (PMID 36598219, 2023). "Furthermore, IL-10 was found to be upregulated in colonic mucosa in patients with remission ulcerative colitis (UC)." (PMID 32695157, 2020). "B10/Th17 ratio and IL-10/IL-17 ratio can be used as prognostic markers for ulcerative colitis." (PMID 29765931, 2018). "B10/Th17 ratio and IL-10/IL-17 ratio can be used as prognostic markers of ulcerative colitis." (PMID 29765931, 2018). "Serums IL-10 and IL-17 in ulcerative colitis patients and healthy subjects were detected by ELISA." (PMID 29765931, 2018). "Furthermore, IL-10 derived from B cells restrains the development of ulcerative colitis by suppressing T helper (TH) 2-type immune pathology and reduces the production of TH2 cell-mediated IL-4, which can trigger the disease." (PMID 29201923, 2017). "Increased IL-10 expression in upregulation of IL-10 and IL-11 anti-inflammatory cytokines through upregulation of regulatory T cells were observed in dextran sodium-sulphate -induced ulcerative colitis mice models upon combined treatment of turmeric essential oils." (PMID 38586374, 2024). "Moreover, the same EPS prevented and ameliorated the inflammatory response of dextran-sulfate-sodium-induced ulcerative colitis in mice by decreasing mouse macrophage inflammatory protein 2 mRNA and stimulating the production of immunoregulatory cytokine IL-10." (PMID 36769176, 2023).
ulcerative colitis (continued). "Also, it has been shown that the abundance of Fusicatenibacter saccharivorans decreases in patients with active ulcerative colitis, but increases in patients with quiescent ulcerative colitis, and the bacterium suppresses intestinal inflammation through IL-10 secretion." (PMID 35602030, 2022). "In the current ulcerative colitis model, the increased expression of mTOR and IL-6 in the colon of ulcerative rats enhanced the generation of Th17 cells and the release of IL-17 and IL-23 in line with reducing the expression of IL-10, the anti-inflammatory cytokine." (PMID 34489707, 2021). "Thus, our data show a protective role of CLP in the model of ulcerative colitis, since the treatment of the animals with this alkaloid negatively regulated the levels of Th1 and Th17 cytokines and increased the production of IL-10, known as a cytokine with anti-inflammatory activity." (PMID 30205459, 2018). "Olsalazine significantly increased the contents of IL-2, IL-10, IL-22, TGF and EGF in ulcerative colitis rats, and significantly decreased the scores of DAI, CMDI, HS and the contents in IL-7, IL-17, TNF-α, IL-1β and IFN-γ when compared with the model group." (PMID 37610966, 2023). "More importantly, the expression of anti-inflammatory cytokine IL-10 and tissue repair gene CD 206 was also enhanced by SHPS-1, resulting in alleviated ulcerative colitis in mice." (PMID 35053927, 2022). "In a study of ulcerative colitis, CD4+CD25+ Tregs in rat peripheral blood were negatively correlated with IL-10 levels." (PMID 32218692, 2020). "We conclude that MRS has a protective effect on acetic acid-induced ulcerative colitis in mice via blocking the TLR4/NF-κB/MAPK signaling pathway and promoting the IL-10/JAK1/STAT3-mediated anti-inflammatory response." (PMID 31182999, 2019). "Here, we test whether IL-10 can favour the response to glucocorticoids by improving the TNFα-induced intestinal barrier damage (assessed by transepithelial electrical resistance) in Caco-2 monolayers, and their possible implications on glucocorticoid responsiveness in active ulcerative colitis." (PMID 26090671, 2015). "Conversely, although treatment with T. spiralis antigen ameliorated all pathological features of ulcerative colitis in induced mice, the serum nitrite levels remained high comparable to those in the TNBS alone group, despite a persistent rise of local IL-10 levels." (PMID 40830617, 2025). "Interleukin-10 is produced naturally in ulcerative colitis, indicating that it is a result of inflammation, not a cause." (PMID 41356879, 2025). "Glycyrrhiza uralensis alleviated intestinal inflammation by inhibiting pro-inflammatory factors (e.g., IL-6 and IL-1β), and mitigated ulcerative colitis by repairing mitochondrial damage and increasing SOD, GSH-PX, and IL-10 levels in intestinal epithelial cells." (PMID 41180229, 2025). "As expected, the VK2 administration substantially alleviated the ulcerative colitis, and it was mainly by decreasing the DAI index, increasing the expression of anti-inflammatory factor IL-10, muc2, and tight junction proteins (ZO-1, occludin), and by improving the intestinal tissue architecture." (PMID 36769323, 2023). "The present study found that APH reduced the inflammatory response by upregulating the content of IL-10 and downregulating the content of TNF-α, IL-1β, and IL-6, which demonstrates that APH could alleviate ulcerative colitis." (PMID 36359970, 2022). "Additionally, increased mucosal T cell activation production of IL-10, TGF-β and FoxP3 were found in the colon of an individual with ulcerative colitis who self-infected with T. trichiura." (PMID 34078488, 2021). "The typical feature of ulcerative colitis was the inflammation of the intestinal mucosa, which resulted from the activation of the immune response by pro-inflammatory mediators (IL-6 and TNF-α) and anti-inflammatory cytokine IL-10." (PMID 35010176, 2021).
ulcerative colitis (continued). "Regardless of whether EP4 agonists elicit all their anti-inflammatory actions through induction of endogenous IL10, an EP4 agonist has now been tested and shown to be effective in phase 2 trials of ulcerative colitis." (PMID 32240179, 2020). "Studies indicate that they may be beneficial in treating ulcerative colitis (UC) by modulating intestinal immunity and reducing proinflammatory cytokines such as TNF-α and IL-1β while increasing anti-inflammatory factors like IL-10." (PMID 40077619, 2025). "Moreover, an RCT conducted in patients with ulcerative colitis showed that butyrate enemas significantly increased the colonic IL-10/IL-12 ratio in mucosal biopsies, however not significantly when compared to the placebo group." (PMID 36904292, 2023). "It was suggested that olsalazine has a therapeutic effect on ulcerative colitis induced by DSS in mice, and the mechanism may be related to the increase of IL-2, IL-10, IL-22, TGF, and EGF and the decrease of the expression of IL-7, IL-17, TNF-α, IL-1β, and IFN-γ." (PMID 37610966, 2023). "The fact that the FMT (control) treatment could not reverse the decrease of IL-10 by DSS may be owing to the fact that it alleviates DSS-induced ulcerative colitis by increasing the acetic acid producing bacteria." (PMID 35268045, 2022). "That disease activity correlated with circulating concentrations of IL17, IL10, IL8, IL6 and interferon‐γ when assessed in cross‐sections of patients with ulcerative colitis is not new, as was the poor correlation with levels of TNFα." (PMID 40584280, 2025). "The wild-type (WT), TLR4, TLR2, and IL-10 knockout (-/-) germ-free mice grown were with or without BF colonization for 28 days, and then administered 1% DSS in drinking water for 7 day to induce acute ulcerative colitis." (PMID 28683149, 2017).